CPB1 (carboxypeptidase B1)
Synonyms: PASP; CPB; PCPB
Tractability: Small molecule: a high-quality ligand is known; it has a binding pocket of medium quality; it belongs to a druggable protein family. Antibody: UniProt places it where antibodies can reach, with medium confidence; UniProt predicts a signal peptide or a membrane-spanning region; its Gene Ontology location is reachable by antibodies, with medium confidence. PROTAC: a small molecule that binds it is known.
Target class: Metallo protease; Metallo protease MC clan; Protease; Metallo protease M14A subfamily; Enzyme
Gene: Protein-coding gene on chromosome 3 (148,791,102 to 148,860,187, forward strand). Ensembl gene ENSG00000153002.
Subcellular location: Secreted; Zymogen granule lumen
Subcellular location (Human Protein Atlas): Endoplasmic reticulum; Predicted to be secreted
Pathways (Reactome):
Developmental Biology: Developmental Lineage of Pancreatic Acinar Cells
Metabolism of proteins: Metabolism of Angiotensinogen to Angiotensins
Gene Ontology:
Molecular function: carboxypeptidase activity; metallocarboxypeptidase activity; protein binding; zinc ion binding
Biological process: proteolysis
Cellular component: extracellular region
Genetic constraint (gnomAD): Loss-of-function variants: 47 observed, 51.35 expected, observed/expected ratio (o/e) 0.92, 90% interval 0.72 to 1.17. The upper end of that interval is the gene's LOEUF score, 1.17, which puts it in group 5 of 6, group 1 being the genes least tolerant of losing a copy. Missense variants: 477 observed, 525.93 expected, observed/expected ratio (o/e) 0.91, 90% interval 0.84 to 0.98. Synonymous variants: 187 observed, 194.03 expected, observed/expected ratio (o/e) 0.96, 90% interval 0.86 to 1.09.
Homologues: Orthologues: chimpanzee CPB1 (98% identical), macaque CPB1 (94% identical), pig CPB1 (83% identical), rabbit CPB1 (79% identical), guinea pig CPB1 (76% identical), rat Cpb1 (76% identical), mouse Cpb1 (74% identical), tropical clawed frog cpb1 (59% identical), zebrafish cpb1 (58% identical), Caenorhabditis elegans T06A4.1 (37% identical), Caenorhabditis elegans Y47G6A.19 (36% identical), Drosophila melanogaster CG7025 (33% identical), and 14 more. Paralogues in human: CPA3 (49% identical), CPA1 (43% identical), CPA6 (41% identical), CPA4 (41% identical), CPB2 (41% identical), CPA2 (41% identical), CPA5 (38% identical), CPO (36% identical).
Diseases named in the same sentence as CPB1 in open-access papers:
CPB1 is named in the same sentence as 43 diseases in open-access papers, as found by Europe PMC text mining. Sharing a sentence is not in itself a finding about the gene and the disease. The quoted sentences say what the papers report.
pancreatic cancer (11 papers, 2020 to 2025). "In another study, it was reported that mutations in CPB1 were associated with pancreatic cancer." (PMID 38608280, 2024). "The CPA1 and CPB1 variants induced by ER stress are associated with pancreatic cancer development." (PMID 35686102, 2022). "GSEA also further confirmed the plausibility of the PPI results, e.g. ABL protein enrichment in the pancreatic adenocarcinoma pathway, pancreatic cancer, CPB1 enrichment in the metabolism of angiotensinogen to angiotensins, and peptide hormone metabolism." (PMID 36261459, 2022). "Both CPB1 and CPA1 were reported as susceptible genes of pancreatic cancer." (PMID 33197880, 2020). "The CPB1 gene may be related to the structural components in extracellular matrix of the pancreatic cancer cell." (PMID 32272917, 2020). "For CPB1, immunohistochemistry of tissue microarray from patients with PDAC showed that it was significantly downregulated in pancreatic tumor compared with adjacent normal pancreatic tissues." (PMID 38608280, 2024).
breast carcinoma (4 papers, 2020 to 2025). "CPB1 can obviously differentiate DCIS from the other subtypes of breast cancer." (PMID 39804726, 2025). "However, upon stratification by breast cancer subtype, there was hardly any expression of CPB1 in young TNBC African patients." (PMID 36685821, 2022). "In domain 1, CPB1 can significantly distinguish DCIS from other subtypes of breast cancer." (PMID 36250636, 2022).
acute pancreatitis (2 papers, 2021 to 2023). An acute inflammatory process that leads to necrosis of the pancreatic parenchyma. "Carboxypeptidase B1, cleaves the C‐terminal of lysine or arginine, used as a serological marker of acute pancreatitis." (PMID 37249284, 2023). "However, CPB1 is abundant in plasma, and considered a biomarker of acute pancreatitis." (PMID 34246984, 2021).
epilepsy (2 papers, 2018 to 2023). A brain disorder characterized by episodes of abnormally increased neuronal discharge resulting in transient episodes of sensory or motor neurological dysfunction, or psychic dysfunction. "For instance, the human CPB1 gene, which is orthologous to 8 of these 244 epilepsy-related genes in Drosophila, encodes the pancreatic secretory enzyme carboxypeptidase B1." (PMID 36873106, 2023).
Sepsis (2 papers, 2019 to 2023). Sepsis is defined as life-threatening organ dysfunction caused by a dysregulated host response to infection. "Caspase-11-dependent cell death in macrophages can also be initiated by the protein carboxypeptidase B1 (Cpb1), a complement-related protein, via the Cpb1–C3–C3aR signaling pathway in a mouse endotoxemia sepsis model." (PMID 37664463, 2023). "Cpb1 binds to and activates C3aR and thus regulates innate immune signaling, and caspase-11 expression amplifies MAPK activity and IFN-α-receptor activation downstream of TLR4 and influences disease severity in LPS-induced sepsis and endotoxemic mice." (PMID 31671729, 2019).
Constipation (1 paper, 2024). Infrequent or difficult evacuation of feces. "The present results suggest that C3 deficiency-induced constipation may be associated with 1237 upregulated genes including PNLIP, CEL, CPB1, CTRL, PNLIPRP1, and REG1 as well as 1292 downregulated genes including Eif2s3y, UTY, KDM5D, IGKV6-32, Olfr870, and DDX3Y." (PMID 39273477, 2024).
cyst (1 paper, 2021). A sac-like closed membranous structure that may be empty or contain fluid or amorphous material. "Such comparison resulted in 4 upregulated (CP, CEACAM5, DMBT1, and KRT6A) and 8 downregulated (CEL, CPA1, CPB1, ALB, SERPINA4, CA2, CLU, and AMBP) DEGs secreted in cyst fluid of high-risk IPMNs." (PMID 34790815, 2021).
diabetes mellitus (1 paper, 2023). A metabolic disorder characterized by abnormally high blood sugar levels due to diminished production of insulin or insulin resistance/desensitization. "In the unhealthy population they co-occur with REG1A, REG1B, CPB1, and REG3A, all involved in diabetes mellitus and malignant neoplasms." (PMID 37021928, 2023).
ductal carcinoma in situ (1 paper, 2024). "The overexpression of carboxypeptidase B1 (CPB1) is bound up with ductal carcinoma in situ and is bond with better survival outcomes, Consistent with Jun Han's findings." (PMID 38586328, 2024).
enterotoxemia (1 paper, 2023). Disease caused by the liberation of exotoxins of clostridium perfringens in the intestines of sheep, goats, cattle, foals, and piglets. "Clostridium perfringens beta-1 toxin (CPB1) is responsible for necrotizing enteritis and enterotoxemia." (PMID 37368667, 2023).
Insulin resistance (1 paper, 2019). Increased resistance towards insulin, that is, diminished effectiveness of insulin in reducing blood glucose levels. "Chemokine (C-C motif) ligand 21 (CCL21), CYP27A1, RPRM, and CPB1 are novel biomarkers for the development of insulin resistance." (PMID 30678306, 2019).
pancreatic exocrine insufficiency (1 paper, 2021). "CEL, CPA1, and CPB1 code for carboxyl ester lipase, carboxypeptidase A1, and carboxypeptidase B1, respectively, and their downregulation is again indicative of pancreatic exocrine insufficiency associated with onset of malignancy in benign IPMNs." (PMID 34790815, 2021).
tumor (9 papers, 2016 to 2026). "In contrast, domain 13, with high expression of MGP, CPB1, and S100G, points to a region associated with calcification, ECM remodeling, and tumor progression, which may contribute to treatment resistance and poor clinical outcomes." (PMID 41223185, 2025). "We analyzed the effect of CPB1 both as a tumor suppressor and in oncogenic signaling." (PMID 33917306, 2021). "We then went on to answer the question as to whether the expression of CPB1 changes as the tumor progresses." (PMID 33917306, 2021). "In Cluster 10 (DCIS/LCIS), upregulated genes such as CPB1, COX6C, TFF3, and IL6ST reflect early-stage tumor characteristics and immune regulation." (PMID 41182757, 2025).
cancer (8 papers, 2016 to 2025). A tumor composed of atypical neoplastic, often pleomorphic cells that invade other tissues. "In recent years, there have been relatively few researches on the association between CPB1 gene and malignant tumors." (PMID 32272917, 2020). "We then compared the expression pattern of CPB1 in normal breast tissues (N = 475) vs. BC tissues (N = 5574) from GENT2 dataset and found a slight decrease in overall {mean: 7.8 (normal), 7.02 (cancer); median: 7.47 (normal), 6.13 (cancer)} expression of CPB1 in BC patients (p-value < 0.0001)." (PMID 33917306, 2021).
infection (7 papers, 2010 to 2025). The state of being infected such as from the introduction of a foreign agent such as serum, vaccine, antigenic substance or organism. "In other word, APOC4 and CPB1 proteins were damaged, which may be associated with the degree of infection." (PMID 34035220, 2021). "More recently, the same research group also demonstrated that H. capsulatum Cpb1 accesses the macrophage cytosol during infection, suggesting the cytosol of the host cell as the site of action where Cpb1 would actively induce an integrated stress response." (PMID 36266777, 2022). "For the hub response genes of E. coioides, IL6 and IL1B were induced, while CELA2, TRY, CPA1, CPA2, and CPB1 were repressed throughout the infection process." (PMID 31130962, 2019). "TRY, CPA1, CPA2, and CPB1 were considered as hub genes and proven to be repressed throughout the infection process by qRT-PCR." (PMID 31130962, 2019). "Our results demonstrate the existence of a novel virus-control mechanism by CPB1 in the ER of Ae. aegypti midgut cells during DENV2 infection." (PMID 25521592, 2014).
bacterial infection (1 paper, 2022). "Moreover, the rbohD cpb-1 double mutant was more susceptible to bacterial infection than WT seedlings or the respective single mutants, indicating that RBOHD and CP are both positive regulators of defense." (PMID 35269589, 2022).
CPB1 also shares sentences with these, for which no sentence is quoted: Cirrhosis (3 papers); liver cirrhosis (2); pulmonary hypertension (2); atypical ductal hyperplasia (1); breast disease (1); colonic neoplasm (1); colorectal cancer (1); corneal infection (1); COVID-19 (1); delirium (1); Emphysema (1); endometritis (1); epithelioid mesotheliomas (1); gastrointestinal tumors (1); heart failure (1); Hepatitis (1); keratitis (1); liver cancer (1); liver failure (1); microcephaly (1); Mitral regurgitation (1); neurological disorders (1); overlap syndrome (1); pancreatic adenocarcinoma (1); pancreatitis (1); pulmonary edema (1); pulmonary embolism (1).